AIM2 (absent in melanoma 2)
Diseases named in the same sentence as AIM2 in open-access papers (continued):
Sharing a sentence is not in itself a finding about the gene and the disease.
infection (continued). "Based on these observations, we postulated that dysfunctional mitochondria might be removed early during F. tularensis LVS infection to avoid stimulating Aim2-mediated responses by the leaked mtDNA." (PMID 37266012, 2023). "Besides, monocytes infection activates AIM2 inflammasome, caspase-1 and GSDMD cleavage, and the expression level of GSDMD on the cell membrane and cytoplasm of monocytes is linked with the severity of infection." (PMID 37063905, 2023). "In contrast, F. novicida-infected wild-type BMDMs produced very high levels of IFN-β in a STING-dependent manner, and these levels remained significantly elevated in Aim2−/− BMDMs at 12 and 24 post-infection and in immortalized Gsdmd−/− BMDMs 24 h post-infection." (PMID 37266012, 2023). "In parallel, consistently, AIM2 deficiency could prevent the increase of kidney bacterial burden due to the mutant infection, indicating that the resulting bacterial dissemination is mediated by AIM2." (PMID 36128739, 2022). "Infection of these cells with MCMV efficiently induced AIM2-dependent inflammasome activation." (PMID 35464953, 2022). "In addition, AIM2 knockout mice are more susceptible to Brucella infection and infection of C57BL/6, NLRC4, NLRP3, AIM2, ASC and Caspase-1 KO (knockout) BMDM (bone marrow-derived macrophage) with B. abortus than wild-type control mice." (PMID 36068262, 2022). "A mutant virus lacking VP22 (HSV1ΔVP22) infection results in diminished viral yields in vivo, but HSV1ΔVP22 replication is largely restored in AIM2-deficient mice." (PMID 35464953, 2022). "Neutrophils are swiftly attracted to areas of cell or tissue injury upon infection or inflammation and release multiple cytokines, including IL‐1β.92, 93, 94 Key components of the AIM2 inflammasome complexes are highly expressed, mainly in the cytoplasm of neutrophils." (PMID 34014039, 2021). "Aim2, in particular, is important for innate immunity against infection with F. novicida." (PMID 34690967, 2021). "However, inflammasome activation and cell death were also partially reduced in Mefv–/– BMDMs during HSV1 and F. novicida infections, suggesting that these infections activate Pyrin to drive AIM2-mediated inflammatory signaling and cell death." (PMID 34471287, 2021). "The importance of AIM2 during mycobacterial infection is supported by data with BCG, where repeated infection of WT and Aim2-KO mice vial the tail vein showed KO mice were defective in controlling bacterial burden which was associated with altered immunity (enhance type I IFN, reduced type II IFN)." (PMID 34276708, 2021). "In contrast, treatment with poly(dA:dT) allowed interactions between endogenous ASC, AIM2 and caspase-1, but not Pyrin, ZBP1, caspase-8, RIPK3, RIPK1 or FADD, suggesting that infection has a distinct ability to form this AIM2 multi-protein cell death-inducing complex." (PMID 34471287, 2021). "During the infection, it has been demonstrated that the presence of GBPs lead to cytosolic lysis of F. novicida and the released DNA may serve as a scaffold for AIM2 oligomerization." (PMID 35004352, 2021). "Based on previously published findings, we hypothesised that Mtb induces the assembly of one of the ASC-dependent inflammasomes, NLRP3 or AIM2, upon infection of macrophages." (PMID 32385301, 2020). "Furthermore, it has been reported the relevance of GBPs in the AIM2 DNA sensing during an infection model." (PMID 32973778, 2020). "Notably, the AIM2 inflammasome is involved in the activation of mouse macrophages during infection with a virulent M. bovis strain presumably translocated to the cytosol." (PMID 32373118, 2020). "Mice that lack AIM2 can support infection of a VP22-null HSV-1." (PMID 33374862, 2020). "Our previous studies show that infection with either P. vivax or P. falciparum prime circulating monocytes to express an inflammasome gene signature, form AIM2, NLRP3, and NLRP12 specks, express active caspase-1, and produce high levels of IL-1β, when challenged with LPS18,19,32." (PMID 32929083, 2020).
infection (continued). "Importantly, the abundance of AIM2, whose expression was upregulated by IFNγ, was unchanged during the course of Tg infection." (PMID 31268602, 2019). "We observed robust IL-1β production in BMDMs from WT and Aim2–/–mice in response to infection with MAYV, but Nlrp3–/–, Asc–/–and Casp1/11–/–macrophages failed to induce IL-1β secretion." (PMID 31479495, 2019). "Taken together, these results suggest that macrophages and cDCs are not required for early IFN-α/β cytokine production (within the first 24 h of infection), but have indispensable roles at the late stage (after 24 h of infection) of YM infection in Nlrp3−/− and Aim2−/− mice." (PMID 30470758, 2018). "In addition, AIM2 protein levels decreased 24 h post infection, which reinforced our unpublished preliminary observations." (PMID 28219398, 2017). "The AIM2 inflammasome is indispensable during certain infections." (PMID 28219398, 2017). "This indicated that pUL83 interacts with AIM2 6 h and 12 h post infection." (PMID 28219398, 2017). "The large number of inflammasome complexes activated upon F. novicida infection is reminiscent of what have been observed during infection with other intracellular bacteria, although F. novicida infection of murine macrophages is somewhat unique due to its high dependence on AIM2." (PMID 28968459, 2017). "However, our previous study has shown that AIM2 is upregulated in murine model of fatal ehrlichiosis at an early stage of infection (Day 3 p.i.)." (PMID 29049365, 2017). "Indeed, at MOI 10, propidium iodide incorporation/fluorescence sharply increased around 6 h post-infection in WT macrophages while Aim2-/- BMDMs presented cell death kinetics delayed by more than 7 h compared with that of WT macrophages." (PMID 28968459, 2017). "Counterintuitively, we found that GBP deficient macrophages demonstrated increased host cell death following infection with strains that specifically activated AIM2, suggesting that during L. monocytogenes infection GBPs act as a negative regulator of AIM2 activation." (PMID 27806131, 2016). "Importantly, suppression of Aim2-dependent inflammasome activation by FLT_0325 inhibits pyroptosis in response to infection by F. tularensis LVS in macrophages." (PMID 24324933, 2013). "Analysis of these events during the late phase of the infection cycle would be very informative and may reveal Mtb-mediated AIM2-inflammasome activation." (PMID 24130966, 2013). "Infection with Ft triggered a predominantly AIM2-dependent IL-1β response." (PMID 23554897, 2013). "In addition, Aim2 and Asc were proposed to trigger caspase-1-independent, caspase-8, -9, -3-mediated apoptosis of macrophages in response to infection with F. tularensis, contributing to restriction of bacterial replication in these cells." (PMID 24324933, 2013). "In addition, mutants lacking FLT_0325 also induce higher levels of caspase-1 activation dependent on Aim2 and Tlr2 and secretion of IL-1β dependent on Tlr2, Aim2, and Nlrp3 in the early periods of infection." (PMID 24324933, 2013). "Taken together, we propose a model in which macrophages integrate signals from the spatiotemporally separated TLR2 signaling pathway and AIM2 inflammasome complex during infection in order to mount an appropriate innate immune response against invading bacteria." (PMID 21698237, 2011). "Additionally, we show that TLR2 contributes to inflammasome activation in response to infection by L. monocytogenes, a cytosolic bacterium that is also recognized by AIM2." (PMID 21698237, 2011). "It would be interesting to test whether TLRs play a role in promoting more rapid AIM2 inflammasome activation during infections with other pathogens that activate AIM2 such as vaccinia virus and murine cytomegalovirus." (PMID 21698237, 2011). "Interestingly, AIM2 has been shown to crosstalk with the apoptosis pathway during infection." (PMID 40006996, 2025).
infection (continued). "Interestingly, the surface of A. fumigatus and C. albicans biofilms is covered with extracellular DNA, which may explain the activation of AIM2 in response to infection." (PMID 41249509, 2025). "Therefore, we conducted infection experiments using Casp11 and Aim2 double knockout cells." (PMID 39998486, 2025). "In order to investigate whether the resistance of Aim2−/− mice to C. albicans infection is linked to AIM2 inflammation, we examined the inflammasome activation levels in the kidneys of WT and Aim2−/− mice after infection." (PMID 38918243, 2024). "Notably, the levels of activated caspase-1 and released IL-1β in response to LPS and ATP, which activate the NLRP3 inflammasome; dsDNA transfection and infection with F. novicida, both as activators of the AIM2 inflammasome, were reduced following transfection with Ncf1, Ncf2, or Ncf4 siRNAs." (PMID 38886341, 2024). "Notably, 50% of Aim2−/− mice remained alive at day 10 post infection." (PMID 38918243, 2024). "The AIM2 inflammasome could trigger the innate immune response by producing mature proinflammatory cytokines such as IL-18 and IL-1β, and it might also activate cell necroptosis when facing infections." (PMID 36742336, 2023). "Therefore, specific dsDNA motifs, methylation of CpG islands of host DNA, or GSDMD-dependent transcription of viral genomes may trigger activation of the AIM2 in infections by these viruses." (PMID 37515138, 2023). "Moreover, Mtb-mediated AIM2 inflammasome inhibition is dependent on a functional ESX-1 secretion system since infection with the Mtb strain deficient in esxA fails to inhibit IL-1β secretion induced by Msme." (PMID 35237260, 2022). "Herpes simplex virus 1 (HSV1), a dsDNA virus that causes lifelong incurable, recurrent pathologies, and Francisella, a gram-negative bacteria that can cause rapid lethality upon infection, are two diverse pathogens that are known to activate the AIM2 inflammasome and cell death." (PMID 34471287, 2021). "In addition to F. novicida, AIM2 is important for inflammasome activation during infection with Listeria monocytogenes, Mycobacterium tuberculosis, Porphyromonas gingivalis, Streptococcus pneumoniae, vaccinia virus, and mouse cytomegalovirus, but not S. typhimurium infection." (PMID 25879288, 2015). "Furthermore, Mtb could inhibit AIM2-inflammasome activation induced by infection with either Msme or the transfection of dsDNA." (PMID 24130966, 2013). "Since we have shown that TLR2 is required for rapid inflammasome activation in response to F. novicida, we tested whether TLR2 plays a similar role in inflammasome activation during infection with another cytosolic bacterial pathogen known to activate the AIM2 inflammasome, Listeria monocytogenes." (PMID 21698237, 2011). "The HF strain robustly induces AIM2-dependent inflammasome activation, whereas the F and KOS strains elicit minimal responses despite comparable infection efficiency." (PMID 41974701, 2026). "To further confirm the formation of this multiprotein complex, we observed the colocalization of ASC specks with AIM2 and CASP1 within the same cell at 24 h post-MPXV infection." (PMID 41225161, 2025). "Following high-dose infection (105 PFU), untreated CAST/EiJ mice died within 8 days, whereas AIM2 inhibitor treatment (ODN TTAGGG sodium) significantly prolonged survival, with 10% of treated mice surviving the infection." (PMID 41225161, 2025). "In Aim2–/– iBMDMs, compared with WT control cells, MPXV-infected cells presented significantly elevated viral DNA levels at 24 h post-infection." (PMID 41225161, 2025). "Many sensor proteins (e.g., cGAS, AIM2, and TLR9) recognize the molecular signature of infection or stress and are responsible for the innate immune response to DNA." (PMID 38343534, 2024). "Surprisingly, our findings reveal that, in contrast to its protective role in other types of infection, nucleic acid-sensing PRR AIM2 actually enhances C. albicans infection." (PMID 38918243, 2024).
infection (continued). "Compared with WT BMDMs, the activation of CASP1/GSDMD/GSDME, CASP8/3/7, and RIPK3/MLKL in Mefv–/– and Zbp1–/– BMDMs decreased after infection with HSV1 or F. novicida, and completely inactive in Aim2–/– and Mefv–/–Zbp1–/– BMDMs." (PMID 36845112, 2023). "Infection of macrophages with IAV triggers the release of ox-mtDNA and activation of NLRP3 and AIM2 inflammasomes." (PMID 37001140, 2023). "The host detects pathogen invasion through cytosolic PRRs such as NLRP3, AIM2, and NLRC4, and induces immune responses to resistant infection through the inflammasome assembly." (PMID 38136879, 2023). "For example, in the infection of HSV-1 and Francisella novicida, AIM2 PANoptosome, whose assembly is driven by AIM2, pyrin, and ZBP1, can mediate PANoptosis, resulting in inflammatory cell death." (PMID 37122745, 2023). "To investigate this further, we measured LDH release as a readout for pyroptosis in wild-type, Aim2−/− and immortalized Gsdmd−/− BMDMs infected with F. tularensis LVS or F. novicida at 24 h post-infection." (PMID 37266012, 2023). "We now know that Mtb is able to inhibit the AIM2- and NLRP3-inflammasome during ex vivo infections but is there a role for the inflammasome for increasing host resistance or susceptibility during in vivo Mtb infections?" (PMID 35237260, 2022). "In conclusion, T.marneffei induces pyroptosis in hepatocytes through activation of the AIM2-caspase-1/-4-GSDMD axis, which may be an important cause of liver damage, and other death pathways including necroptosis and apoptosis may also be involved in the later stage of infection." (PMID 35639503, 2022). "At 3 weeks after infection, the levels of IL-1β in BALF and IL-18 in serum from Aim2-/- mice are lower than that from WT mice." (PMID 33503864, 2021). "We next examined RhoA-GTP levels in Aim2–/–, Asc–/– and Casp1–/– BMDMs during HSV1 and F. novicida infections." (PMID 34471287, 2021). "Next, we sought to understand the molecular relationship between AIM2, Pyrin and ZBP1 in inducing inflammatory cell death, PANoptosis, during HSV1 and F. novicida infections." (PMID 34471287, 2021). "We also observed that ASC specks colocalized with AIM2, Pyrin and ZBP1 collectively in the same cell at 12 hours post-infection with HSV1 or F. novicida." (PMID 34471287, 2021). "In this review, we focus on activation and regulation of the NLRP3 and AIM2 inflammasomes after exposure to MTB, as well as the effect of inflammasome activation on host defense against the infection." (PMID 33503864, 2021). "Overall, our findings identify a critical interaction between AIM2, Pyrin and ZBP1 that drives innate immune responses during pathogen infection." (PMID 34471287, 2021). "The ISD bait method was validated by identifying known dsDNA sensors including HMGB1, HMGB2, and HMGB3, components of the AIM2 inflammasome, and the SET complex that plays a role in HIV-1 retroviral detection and infection." (PMID 33042865, 2020). "UPEC significantly decreased the gene expression of CASP4, NLRP1, NLRC4, NLRP6 and AIM2 at MOI 1 and MOI 10 after 3 h of infection compared to unstimulated cells." (PMID 33318544, 2020). "POP3, through interactions with AIM2 and IFI16, blocks inflammasome responses induced by infection with dsDNA viruses, including Vaccinia virus (AIM2), CMV (AIM2), and KSHV (IFI16)." (PMID 32962268, 2020). "Infection of AIM2-/- mice with a VP22-null HSV-1 results in 3 logs higher viral yield than infection of AIM2+/+ mice, suggesting that VP22 promotes neuronal spread by inhibiting an AIM-2-dependent host response against HSV-1 infection." (PMID 33374862, 2020). "When infection experiments were performed in the presence of glyburide, a compound that inhibits NLRP3 inflammasome, or A151, a specific AIM2 inhibitor, the secretion of IL-1β was significantly inhibited with respect to uninfected controls." (PMID 32038610, 2019).
infection (continued). "Cells were harvested at 2, 8, and 24 h post-infection and the level of expression of NLRP3, NLRP6, NLRP12, IFI16, and AIM2 was determined by western blot." (PMID 31367214, 2019). "We found that mPDCA-1-mediated depletion of pDCs in Aim2−/−, Nlrp3−/−, Casp1−/−, and Il1r1−/− mice markedly decreased serum levels of IFN-α/β at day 1 after YM infection, compared with those treated with control antibody." (PMID 30470758, 2018). "During in vitro infections, IL-1β secretion was lower in alveolar macrophages from caspase-1/11, NLRP3 or AIM2 KO mice than in WT controls." (PMID 30456207, 2018). "In this study, we found that macrophage infection with LgyLRV1+ parasites resulted in the transcriptional up-regulation of several inflammasome components such as caspase-1, IL-1β, NLRP3, and AIM2." (PMID 29487860, 2018). "To clarify the role of the AIM2 and NLRP3 inflammasomes in M. bovis-infected THP-1 macrophages, we quantified their expression following infection." (PMID 27043315, 2016). "Downregulation of AIM2 expression increased LC3-II and reduced the autophagic adaptor p62 protein at 4h post-infection." (PMID 27409673, 2016). "Infections at various MOIs showed that M. bovis-induced upregulation of both NLRP3 and AIM2 was dose-dependent." (PMID 27043315, 2016). "At 6 h after B. melitensis 16M infection, NLRP3 and AIM2 in the O-A and OA-IA cells were significantly higher than in the control cells (P < 0.01), indicating that at 6 h B. melitensis 16M infection activated NLRP3 and the AIM2 inflammasome." (PMID 27907115, 2016). "To further elucidate the influence of the AIM2 inflammasome on M. bovis-induced autophagy, immunofluorescence was used to detect the amounts of LC3 and SQSTM1/p62 in BMDMs at 24 h post-infection and we saw increased LC3 and decreased SQSTM1/p62." (PMID 27409673, 2016). "The human interferon-inducible PYHIN proteins, AIM2, IFI16, IFIX, and MNDA, have recently emerged as critical cellular factors in mediating both intrinsic and innate immune responses to pathogen infection and tumorigenesis." (PMID 25665578, 2015). "Recent studies from several laboratories, including ours, have established the PYHIN proteins AIM2 and IFI16 as sensors of viral dsDNA, important for eliciting immune and inflammatory responses to infection." (PMID 25665578, 2015). "Upon infection, as observed with ASC specks, AIM2 specks were detectable 2 h earlier in Casp1KO than in WT macrophages." (PMID 23630667, 2013). "Due to the sequential activation of TLR2 and the AIM2 inflammasome during F. novicida infection of macrophages and the critical role that both of these recognition systems play in host defense against this bacterium, we tested whether these systems cooperate during infection." (PMID 21698237, 2011). "Upon examination, we do observe upregulation of AIM2 expression in GC B cells following infection, however we do not see a significant impact of AIM2 activity on GCs and TFH cells." (PMID 40825032, 2025). "Moreover, increased viral dissemination was evident in Aim2–/– mice compared with WT mice, as substantiated by significantly amplified MPXV viral staining in their lungs at 7 days post-infection." (PMID 41225161, 2025). "Finally, in vivo therapeutic experiments demonstrated that oligonucleotide-mediated inhibition of AIM2 in CAST/EiJ mice increased survival and attenuated proinflammatory cytokine production, cell death, and tissue damage following MPXV infection." (PMID 41225161, 2025). "In general, upon a signal indicating infection or cellular damage by other receptor stimuli, NLR (nucleotide-binding domain, leucine-rich repeat containing) or PYHIN family (in case of AIM2) oligomerizes and a larger multiprotein complex is formed by recruiting additional components." (PMID 39290706, 2024).